ENO1 (enolase 1)
Diseases named in the same sentence as ENO1 in open-access papers (continued):
Sharing a sentence is not in itself a finding about the gene and the disease.
lymph node metastasis (6 papers, 2018 to 2022). "The results of the clinicopathological correlation study revealed that ENO1 overexpression was significantly associated with lymph node metastasis (P = 0.003), distant metastasis (P = 0.015) and TNM stage (P < 0.001)." (PMID 31889896, 2019). "Furthermore, the ENO1 level was closely associated with the lymph node metastasis and the prognosis of PDAC." (PMID 29483925, 2018). "Univariate analysis demonstrated that the depth of invasion (P<0.01), lymph node metastases (P<0.05), nerve invasion (P<0.05), TNM stage (P<0.05), and ENO1 expression were associated with worse survival." (PMID 36620599, 2022). "Subgroup analysis showed that high ENO1 expression was associated with worse prognosis, regardless of age, gender, lymph node metastasis, degree of differentiation, neural invasion, and TNM stage (P<0.05)." (PMID 36620599, 2022). "In addition, univariate Cox regression analysis showed that preoperative blood glucose (P < 0.001), lymph node metastasis (P = 0.013), distant metastasis (P < 0.001), TNM stage (P = 0.006) and ENO1 expression (P = 0.001) were associated with OS." (PMID 31889896, 2019). "We demonstrated that ENO1 overexpression is positively correlated with clinical stage, lymph node metastasis, and poor prognosis of PDAC; ENO1 may function as a hopeful candidate diagnostic marker in combination with CA19-9 in PDAC diagnosis." (PMID 29483925, 2018). "Further analysis showed the level of ENO1 in lymph node metastasis group (9.23 ± 4.68 ng/ml) was higher than that in no lymph node metastasis group (6.51 ± 4.69 ng/ml) (P < 0.01)." (PMID 29483925, 2018). "Interestingly, ENO1 expression was higher in patients with lymph node metastasis than in those without (p < 0.05) and the expression level of ENO1 was higher in the primary lesions of OSCC patients with pathologically positive lymph node metastasis by IHC staining." (PMID 36361568, 2022).
multiple myeloma (6 papers, 2017 to 2025). "In recently, the preclinical evidence demonstrates that targeting ENO1 induces plasmacytoid dendritic cells triggered T and NK cell mediated anti-multiple myeloma activity." (PMID 34671213, 2021). "The expression of NEK2 and glycolysis-enhancing genes, such as hexokinase 2 (HK2), alpha-enolase (ENO1), and lactate dehydrogenase A (LDHA), was significantly increased in high-risk myeloma samples and positively correlated each other." (PMID 28086949, 2017). "As well as the combination of ENO1 inhibitor and anti-PD-L1 antibody or HDAC6 inhibitor synergistically enhances the activity of autologous multiple myeloma specific CD8+ T cells." (PMID 34671213, 2021). "Consistently, the expression of HK2, ENO1, LDHA, glucose transporter type 4 (Glut4), and monocarboxylate transporter 4 (MCT4) was downregulated in NEK2 silenced myeloma cells." (PMID 28086949, 2017). "A similar phenomenon has been observed in patients with multiple myeloma, where protein analysis confirmed that ENO1 is not restricted to tumour cells, but also increased in surrounding bone marrow plasmacytoid dendritic cells." (PMID 38473245, 2024).
metastatic tumors (5 papers, 2013 to 2025). "(2024), which reported ENO1 overexpression in invasive ductal carcinomas, high-grade, advanced, and metastatic tumors, associated with worse survival." (PMID 41179678, 2025). "Immunohistochemistry confirmed that ENO1 expression was elevated in the metastatic tumors compared with the primary tumors." (PMID 23504277, 2013). "In the present study of clinical tumor samples, we identified the expression of TAGLN2 in primary tumors and we also identified TPI-1 and ENO1 in metastatic tumors, predominantly by LC–MS/MS." (PMID 23504277, 2013). "In this study, expression of TPI-1 and ENO1, which enhances cancer cell survival and proliferation, were higher in metastatic tumors than in primary tumors, and TAGLN2, which suppresses invasion of cancer cells, was lower in metastatic tumors than in primary tumors." (PMID 23504277, 2013). "Four other glycolytic genes, ENO1, PGM1, LDHB, and PGK19, were upregulated in metastatic tumors compared to non-metastatic tumors." (PMID 40821334, 2025).
Sepsis (5 papers, 2025 to 2026). Sepsis is defined as life-threatening organ dysfunction caused by a dysregulated host response to infection. "We demonstrate that sepsis‐associated lactate accumulation induces P300‐mediated lactylation of ENO1 at lysine 71 in ECs." (PMID 41532698, 2026). "We found that elevated lactate in sepsis promoted the lactylation of ENO1 at the K71 residue, facilitated by the increased activity of the lactyltransferase P300." (PMID 41532698, 2026). "Collectively, these findings suggested that P300 promoted the lactylation of ENO1 in ECs, leading to endothelial dysfunction and increased vascular permeability in sepsis." (PMID 41532698, 2026). "Our previous experiments suggested that targeting LDHA or P300 can inhibit the lactylation of ENO1 in ECs, thereby improving survival in a mouse model of sepsis." (PMID 41532698, 2026). "In summary, we found that an elevated lactate level in sepsis promotes the lactylation of ENO1 K71 in ECs via the action of P300." (PMID 41532698, 2026). "Together, these findings identify ENO1 lactylation as a critical molecular link between metabolic dysregulation and endothelial barrier failure in sepsis." (PMID 41532698, 2026). "By integrating these proteomic results with lactylation profiling, we identified ENO1—a key glycolytic enzyme, as a likely contributor to endothelial dysfunction in sepsis." (PMID 41532698, 2026). "This work reveals a previously unrecognised post‐transcriptional mechanism controlling VE‐Cadherin stability and highlights ENO1 lactylation as a potential therapeutic target for vascular protection in sepsis." (PMID 41532698, 2026). "Here, we investigated the role of enolase 1 (ENO1) lactylation in modulating the functions of endothelial cells (ECs) in sepsis pathogenesis." (PMID 41532698, 2026). "NETs-MPO-anchored ENO1 mediates the role of NETs-DNA in promoting Treg differentiation and function in sepsis-induced immunosuppression via a newly identified DNA sensor IFITM2." (PMID 40892462, 2025). "The expression of IFITM2 in splenic Tregs was also reduced in Eno1fl/fl Cd4Cre mice during septic immunosuppression, suggesting that the upregulation of IFITM2 in sepsis is related to ENO1." (PMID 40892462, 2025). "Data showed that there was a significantly elevated level of ENO1 on the surface of Tregs derived from sepsis patients compared with those derived from healthy controls." (PMID 40892462, 2025). "CD38high C1 monocytes of the Sepsis group highly expressed oxidative stress related genes and glycolysis signature related genes, such as ENO1, PKM, PGK1, and LDHA, which were key glycolytic enzymes." (PMID 40145840, 2025). "In this study, we observed an increased expression of ENO1 in sepsis and found that it promoted the differentiation and function of Tregs." (PMID 40892462, 2025). "Whether ENO1 undergoes lactylation in sepsis and how such modification affects its RNA‐binding activity and endothelial barrier integrity have not been investigated." (PMID 41532698, 2026). "Overall, we demonstrated the role of NETs in sepsis-induced immunosuppression by enhancing Treg differentiation, identified ENO1 as an anchor of NET-MPO, and elucidated the downstream molecular mechanism by which IFITM2-RAP1B-ERK regulates Treg differentiation." (PMID 40892462, 2025). "However, the expression and function of ENO1 in sepsis still need to be clarified." (PMID 40892462, 2025). "However, the roles of ENO1 in the cytoplasm or nucleus in sepsis need to be further investigated." (PMID 40892462, 2025). "ENO1 inhibition significantly attenuated NET-induced Treg differentiation and alleviated sepsis in mice." (PMID 40892462, 2025). "The study reveals that IL1R2 interacts with ENO1 to inhibit glycolysis-mediated pyroptosis and inflammation in sepsis, suggesting the IL1R2-ENO1 interaction as a promising therapeutic target of sepsis." (PMID 40704655, 2025).
Sepsis (continued). "Here, we initially discovered that cell surface ENO1 on CD4+ T cells acted as a receptor anchored by NET-MPO, facilitating NET accumulation around CD4+ T cells and recruiting IFITM2 as a DNA sensor in sepsis-induced immunosuppression." (PMID 40892462, 2025).
Candidemia (4 papers, 2020 to 2024). A form of invasive candidiasis where species of CANDIDA are present in the blood. "The antibody responses against the selected Candida proteins were evaluated in sera of all patients with candidemia by indirect ELISA, using recombinant Mp65, Als3, Hyr1 or Eno1 as the solid phase antigen." (PMID 38088540, 2024). "All patients showed the presence of IgG antibodies against all tested Candida antigens, namely Als3, Mp65, Hyr1 and Eno1, at levels significantly higher than those of non-candidemia controls." (PMID 38088540, 2024). "A little or lack cross-reactivity of CaS1 scFv to human Eno1 will provide a great value for the possible treatment in human candidemia." (PMID 32326294, 2020). "The additional antigens included two proteins (Als3 and Hyr1) that have been shown to be associated with the filamentous, tissue-invasive forms of Candida albicans, a major candidemia agent, and the Eno1 protein that, like Mp65, is expressed by both the yeast and the filamentous forms." (PMID 38088540, 2024). "We further discovered that mAb 12D9 which targets to Eno1 could prevent host plasminogen being captured by C. albicans and was effective for controlling candidemia in vivo." (PMID 33115324, 2020). "Eno1-IgG antibodies exist in patients with candidemia, so monoclonal antibodies against Eno1 may become one of the promising strategies for C. albicans infection." (PMID 32256459, 2020). "IgG titers (ranges) against the Eno1 and Mp65 antigens, which are expressed by both the yeast and filamentous forms of C. albicans, were not significantly different in patients with candidemia due to C. albicans and those infected by other Candida species." (PMID 38088540, 2024).
chronic pancreatitis (4 papers, 2018 to 2023). A chronic inflammatory process causing damage and fibrosis of the pancreatic parenchyma. "As a vast majority of patients being screened for PDAC are patients who have chronic pancreatitis, to be a good diagnostic tool for PDAC, it is critical to know if ENO1 is present in patients with chronic pancreatitis." (PMID 29483925, 2018). "Although previous study showed no up-regulated expression of ENO1 mRNA in chronic pancreatitis tissues, similar to normal pancreas tissues, in the future study, we will additionally evaluate ENO1 levels of plasma as a distinguishing diagnosis marker in patients with chronic pancreatitis and PDAC." (PMID 29483925, 2018). "ALDH3B1, ENO1, ALDH2, GAPDH, and LDHC had significant differences among grades, while ALDH3B1, PKM, and ALDH3B2 differed among chronic pancreatitis histories." (PMID 36814901, 2023). "It was also proved that the expression of ENO1 was not up‐regulated in chronic pancreatitis, similar to normal pancreas tissues." (PMID 32285549, 2020). "In a second SERPA study, when sera from PDA, non-PDA cancer, chronic pancreatitis, autoimmune disease patients and healthy subjects were compared in terms of antibody reactivity, six isoforms of ENO1 with the same molecular weight but different isoelectric points, were identified." (PMID 29462900, 2018).
endothelial dysfunction (4 papers, 2025 to 2026). In vascular diseases, endothelial dysfunction is a systemic pathological state of the endothelium (the inner lining of blood vessels) and can be broadly defined as an imbalance between vasodilating and vasoconstricting substances produced by (or acting on) the endothelium. "Specially, we found that elevated lactate induces the lactylation of ENO1, which subsequently affects VE‐Cadherin expression and contributes to endothelial dysfunction." (PMID 41532698, 2026). "Targeting the lactylation of ENO1 with a specific inhibitory peptide alleviated endothelial dysfunction." (PMID 41532698, 2026). "In vitro, the overexpression of ENO1 enhanced hypoxia-related endothelial dysfunction in human PAECs, whereas inhibition of ENO1 reversed this condition." (PMID 40725037, 2025). "Given the crucial role of glycolysis in endothelial dysfunction and Eno1's RNA‐binding capability, we selected Eno1 for further investigation to explore the role of lactylation in CXCL12 production." (PMID 40895187, 2025). "More importantly, ENO1 can induce mitochondrial dysfunction by targeting and regulating mitochondria-related genes, triggering oxidative stress and cellular damage, thereby exacerbating endothelial dysfunction." (PMID 40859388, 2025).
lymphoma (4 papers, 2016 to 2024). A malignant (clonal) proliferation of B- lymphocytes or T- lymphocytes which involves the lymph nodes, bone marrow and/or extranodal sites. "In lymphoma, ENO1 expression was generally high and being eight times higher than that observed in benign lymphoid tissues." (PMID 38840205, 2024). "Proteomic analysis of peripheral T-cell lymphomas not otherwise specified (PTCL-NOS) revealed a significantly increased ENO1 level (eightfold) in neoplastic cells compared with the non-lymphoma tissue." (PMID 35204345, 2022).
oral squamous cell carcinoma (4 papers, 2021 to 2025). "While prior studies have implicated extracellular ENO1 in CD14-dependent TLR4 signaling in monocytes and a paracrine ENO1/TLR4/IL-6 axis driving metastasis in oral squamous cell carcinoma, its direct interaction with TLR4 in GBM remained unexplored." (PMID 41353343, 2025). "Alpha-enolase (ENO1), an enzyme that catalyzes glycolysis, is highly expressed in oral squamous cell carcinoma." (PMID 38027016, 2023). "The expression of ENO1 and antibody of ENO1 in the serum can be detected in some of oral squamous cell carcinoma patients 31,101." (PMID 34671213, 2021).
osteosarcoma (4 papers, 2022 to 2025). A usually aggressive malignant bone-forming mesenchymal neoplasm, predominantly affecting adolescents and young adults. "In osteosarcoma studies, it is reported that the transcript levels of ENO1, MSN, and HSP90AB1 were higher in osteosarcoma tissues than in normal tissues." (PMID 37894284, 2023). "The results of univariate Cox regression analysis showed SLC2A1, ENO1, FBP1 and PGM1, while multivariate COX regression analysis showed that SLC2A1 and FBP1 could indicate the prognostic risk of patients in osteosarcoma." (PMID 36316355, 2022).
pancreatic adenocarcinoma (4 papers, 2017 to 2023). "The expression of ENO1 is significantly greater in PAAD (pancreatic adenocarcinoma) tumor tissues (T) than in normal tissues (N) with the highest Log2FC value." (PMID 36845730, 2023).
periodontitis (4 papers, 2012 to 2025). An acute or chronic inflammatory process that affects the tissues that surround and support the teeth. "A recent study showed that anti-ENO1 antibody titers are associated with the severity of periodontitis as well as RA disease activity in RA patients." (PMID 30001173, 2018). "P. gingivalis has been suggested as a link in the association between RA and periodontitis: P. gingivalis expresses peptidylarginine deiminase, which can produce citrullinated peptides upon incubation with human fibrinogen or ENO1." (PMID 30001173, 2018). "In our human study, relatively small number of healthy subject samples were used, and a significant association of anti-ENO1 antibody titers with periodontitis may be achieved in a larger cohort." (PMID 30001173, 2018). "Although TdEno has the highest homology with ENO1 among the enolases of human-associated bacteria, it is expected that not only TdEno but also the enolases of diverse periodontitis-associated bacteria contribute to the production of anti-ENO1 antibodies in periodontitis." (PMID 30001173, 2018). "The aim of this study was to investigate the role of TdEno in the production of anti-ENO1 antibodies and the progression of periodontitis." (PMID 30001173, 2018). "In human subjects with healthy periodontium or chronic periodontitis, a strong positive correlation between the levels of anti-TdEno and anti-ENO1 antibodies was observed." (PMID 30001173, 2018). "The anti-ENO1 antibody titers did not have a significant association with the development of slight periodontitis, either (Odd Ratio: 43.2, p = 0.333)." (PMID 30001173, 2018). "Anti-ENO1 antibodies may contribute to the progression of periodontitis in specific conditions, such as RA." (PMID 30001173, 2018). "In this study, we present our findings that TdEno, the enolase of the periodontal pathogen T. denticola, induces the production of anti-ENO1/mEno1 antibodies through molecular mimicry, but the anti-ENO1/mEno1 antibodies play a minimal role in the progression of periodontitis." (PMID 30001173, 2018). "However, a cross-sectional study cannot conclude if the production of anti-ENO1 antibodies is the result of gingival tissue infection with bacteria i.e. periodontitis or a contributing factor to disease progression." (PMID 30001173, 2018). "Therefore, we hypothesized that anti-ENO1 antibodies produced by molecular mimicry during the antibody response to TdEno may contribute to the progression of periodontitis." (PMID 30001173, 2018). "Although the differences were not significant, both the anti-TdEno and anti-ENO1 antibody titers tended to be lower in healthy subjects than in patients with slight periodontitis." (PMID 30001173, 2018).
retinoblastoma (4 papers, 2013 to 2022). A malignant tumor that originates in the nuclear layer of the retina. "A previous study showed that miR-22 suppresses the proliferation of retinoblastoma cells by inhibiting ENO1, and ENO1 was a target of miR-22." (PMID 34772911, 2021). "Also, it has been proved in retinoblastoma that miR-22-3p targeted ENO1 to inhibit proliferation." (PMID 31767835, 2019).
sarcoma (4 papers, 2019 to 2021). A usually aggressive malignant neoplasm of the soft tissue or bone. "The molecular characteristics of the four molecular subtypes were compared, and we determined three genes, namely, ENO1, ACVRL1 and APBB1IP, which were closely associated with the prognosis of sarcoma." (PMID 33509178, 2021). "The data of sarcoma and functional cancer models indicates that ENO1 may become a new potential target for anticancer therapy." (PMID 34671213, 2021). "In our study, both high-expressed ENO1 and low-expressed APBB1IP were predictive of a poor sarcoma prognosis, suggesting that the three potential prognostic markers were closely associated with known genetic markers." (PMID 33509178, 2021). "RT-qPCR assay results indicated that ENO1 was upregulated, whereas ACVRL1 and APBB1IP were downregulated in Hs 729 sarcoma cells that in 10.014 pRSV-T cells." (PMID 33509178, 2021). "HK2, GLUT1, PGK1, ENO1 and PKM were found positive correlation with SLC25A37 in sarcoma patients." (PMID 32831652, 2020). "Furthermore, the three potential prognostic markers (ENO1, ACVRL1 and APBB1IP) in predicting the sarcoma prognosis of different histological types were examined, due to the sample sizes of DT, MPNST, and SS, the prognostic role of the three genes were analyzed in DL, LMS, MFS and UPS." (PMID 33509178, 2021).
systemic sclerosis (4 papers, 2015 to 2023). A chronic disorder, possibly autoimmune, marked by excessive production of collagen which results in hardening and thickening of body tissues. "There are reports showing the presence of ENO1 antibodies in the serum of systemic sclerosis patients with PAH26 and that ENO1 antibodies in serum induce vascular smooth muscle cell contraction." (PMID 30242159, 2018). "They found silencing ENO1 expression downregulated fibrosis-related proteins, such as COL1α1 (collagen type I alpha 1 chain) and fibronectin, in TGF-β1-stimulated normal lung fibroblasts or diseased lung fibroblasts derived from systemic sclerosis patients." (PMID 37964270, 2023).